ITGB1BP2 (integrin subunit beta 1 binding protein 2)
Description:
May play a role during maturation and/or organization of muscles cells.
Synonyms: MSTP015; CHORDC3; ITGB1BP; MELUSIN
Tractability: No criterion of Open Targets' tractability assessment is met for any kind of drug.
Gene: Protein-coding gene on chromosome X (71,301,747 to 71,305,371, forward strand). Ensembl gene ENSG00000147166.
Subcellular location (Human Protein Atlas): Cytosol
Gene Ontology:
Molecular function: protein binding; zinc ion binding; calcium ion binding; integrin binding
Biological process: centrosome duplication; muscle organ development; signal transduction
Cellular component: Z disc
Homologues: Orthologues: macaque ITGB1BP2 (99% identical), dog ITGB1BP2 (96% identical), rat Itgb1bp2 (93% identical), mouse Itgb1bp2 (93% identical), guinea pig ITGB1BP2 (93% identical), pig ITGB1BP2 (87% identical), chimpanzee ITGB1BP2 (81% identical), rabbit ITGB1BP2 (80% identical), tropical clawed frog itgb1bp2 (49% identical), zebrafish zgc:92429 (47% identical), Drosophila melanogaster mora (39% identical), Caenorhabditis elegans chp-1 (29% identical). Paralogues in human: CHORDC1 (46% identical).
Diseases named in the same sentence as ITGB1BP2 in open-access papers:
ITGB1BP2 is named in the same sentence as 8 diseases in open-access papers, as found by Europe PMC text mining. Sharing a sentence is not in itself a finding about the gene and the disease. The quoted sentences say what the papers report.
cervical cancer (1 paper, 2025). A primary or metastatic malignant neoplasm involving the cervix. "Results from a proximity extension assay study suggested that ITGB1BP2 may be a candidate biomarker for diagnosing invasive cervical cancer." (PMID 39778021, 2025).
Hypertension (1 paper, 2009). The presence of chronic increased pressure in the systemic arterial system. "The three variations of the ITGB1BP2 gene have been detected in families of patients affected either by hypertension or primary hypertrophic cardiomyopathy; however, a clear genotype/phenotype correlation was not evident." (PMID 20017903, 2009).
infection (1 paper, 2022). The state of being infected such as from the introduction of a foreign agent such as serum, vaccine, antigenic substance or organism. "Six out of eight proteins were significant in the longitudinal analysis for at least one effect (time [ITGB1BP2, AXIN1, MMP1, STAMBP] or condition [GH, ITGB1BP2, 4E-BP1]), suggesting their importance both during hospitalization and after infection." (PMID 36405747, 2022).
ITGB1BP2 also shares sentences with these, for which no sentence is quoted: cardiomyopathies (1 paper); dilated (1); hypertrophic cardiomyopathy (1); Obesity (1); type 2 diabetes mellitus (1).